PRSS8 (serine protease 8)
Diseases named in the same sentence as PRSS8 in open-access papers (continued):
Sharing a sentence is not in itself a finding about the gene and the disease.
diabetes (3 papers, 2014 to 2023). "Further studies are needed to clarify pathophysiological significance of circulating PRSS8 in glucose metabolism and diabetes-associated vascular complications." (PMID 34361079, 2021). "Serum PRSS8 results support, collectively, that an improved expression of liver PRSS8 culminates in elevation of this form of PRSS8, which may be involved in the pathophysiology of type 2 diabetes and diabetes-associated atherosclerosis as well." (PMID 34361079, 2021). "By contrast, long-term HSD feeding reduced PRSS8 expression in islets, suggesting its pathological contribution to diabetes." (PMID 37277555, 2023). "Moreover, in humans, serum PRSS8 levels reduced more in type 2 diabetes mellitus (T2DM) patients than healthy controls and were lower in T2DM patients with increased maximum carotid artery intima media thickness (>1.1 mm)." (PMID 34361079, 2021). "Our findings regarding the function of PRSS8 on insulin secretion may add to an improved understanding of the pathophysiologic mechanisms underlying the development of diabetes and indicate the potential usefulness of targeting PRSS8 in the treatment of diabetes." (PMID 37277555, 2023).
esophageal cancer (3 papers, 2016 to 2019). A primary or metastatic malignant neoplasm involving the esophagus. "PRSS8, which encodes a serine protease that has been classified as a tumor suppressor, is downregulated in various cancers, including colorectal, liver, and esophageal cancer." (PMID 31731486, 2019). "We used the approaches of restoration by demethylation, truncated promoter reporters, and knockdown by small interfering RNA, to provide direct evidence identifying the critical role of PRSS8 in esophageal cancer." (PMID 27081034, 2016). "Whether the restoration of PRSS8 expression by DAC could occur in vivo and whether DAC could be used as a potential agent for esophageal cancer therapy need to be firstly tested in animal model." (PMID 27081034, 2016). "More interestingly, the alterations of PRSS8 expression were well correlated with esophageal cancer differentiation and outcomes of the ESCC patients, indicating that PRSS8 might be a useful biomarker for the evaluation of ESCC differentiation and for the prediction of ESCC outcomes." (PMID 27081034, 2016).
gastric cancer (3 papers, 2009 to 2016). A primary or metastatic malignant neoplasm involving the stomach. "The PRSS8 gene was overexpressed 47-fold in urinary bladder cancer, but was downregulated in pancreatic cancer (180-fold) and in stomach cancer (75-fold)." (PMID 27036110, 2016). "Moreover, recent studies have also demonstrated tumor suppressive roles of PRSS8 on prostate, breast, bladder and gastric cancers, in which PRSS8 expression was reduced in prostate, breast, bladder and gastric cancers, due to the hypermethylation of PRSS8." (PMID 27050145, 2016). "PRSS8 was also significantly upregulated in urinary bladder cancer but downregulated in pancreatic and stomach cancer, suggesting that the expression of PRSS8 in tumors may be related to the specific cell or tissue type of tumor origin." (PMID 27036110, 2016).
adenoma (2 papers, 2016 to 2022). A neoplasm arising from the epithelium. "To determine whether loss of PRSS8 occurred in the early stage of tumor progression, we used an online gene expression data set to compare 32 paired patient adenoma tissues and their adjacent normal colonic mucosa (GEO# GDS2947/202525/PRSS8)." (PMID 27050145, 2016). "Upregulated in adenoma samples was a cluster of the proteins FCGBP, SGSH, MUC2, and PRSS8 when compared to adenomas, of which the latter two are known to play an important role in maintaining a healthy colonic epithelium." (PMID 36369736, 2022). "Similar to adenocarcinoma, PRSS8 mRNA was reduced about 50% in adenoma compared to normal mucosa (p<0.0001)." (PMID 27050145, 2016).
atherosclerosis (2 papers, 2020 to 2021). A disease characterized by the build-up of fatty material and calcium deposition in the arterial wall resulting in partial or complete occlusion of the arterial lumen. "TNFRSF4 is involved in atherosclerosis development and tPA is involved in thrombolysis, while PRSS8, FRalpha, MIA, FUR, CDH3 and HE4 are involved in various cancer processes." (PMID 33066363, 2020).
bladder cancers (2 papers, 2013 to 2016). "Loss of PRSS8 in bladder cancer is associated with epithelial to mesenchymal transition – a process during which epithelial cells are converted to migratory and invasive cells." (PMID 27036110, 2016). "We had fully expected that both of these marker genes would present a hypermethylation phenotype in the chronically CSE-treated urothelial cells as RUNX3 hypermethylation in bladder cancer is associated with smoking and PRSS8 hypermethylation correlates with bladder cancer progression." (PMID 23724145, 2013). "But clearly, both RUNX3 and PRSS8 were found to be hypermethylated in bladder cancers or bladder cancer cell lines, with RUNX3 hypermethylation directly associated with bladder cancers of smokers." (PMID 23724145, 2013).
bladder transitional cell carcinoma (2 papers, 2009 to 2025). The most common morphologic subtype of urinary bladder carcinoma (over 90% of cases). "PRSS8 was reported to be associated with epithelial-mesenchymal transition in human bladder transitional cell carcinoma and non-small-cell lung cancer." (PMID 41290592, 2025).
liver cancer (2 papers, 2016 to 2024). An epithelial or non-epithelial malignant neoplasm that arises from the liver. "For example, PRSS8 is a tumor suppressor in colorectal and liver cancer cells." (PMID 38493179, 2024).
Obesity (2 papers, 2021 to 2023). Accumulation of substantial excess body fat. "However, liver substrate proteins of PRSS8 other than TLR4, in this context, remain unclarified, as well as the association between fatty liver or deficient lipid metabolism, brought about by obesity, and PRSS8." (PMID 34361079, 2021).
renal cell carcinoma (2 papers, 2015 to 2016). "Hence, the upregulation of PRSS8 by the ER is likely to have enhanced DNA hypermethylation and led to the regulation of the expression of genes associated with renal cell carcinoma." (PMID 25351113, 2015). "In a recent study, a regulatory network analysis of the estrogen receptor in a model of renal cell carcinoma indicated that estrogen may be involved in regulation of oncogenes and tumor suppressor genes, including PRSS8." (PMID 27036110, 2016).
Barrett esophagus (1 paper, 2016). Esophageal lesion lined with columnar metaplastic epithelium which is flat or villiform. "Moreover, PRSS8 mRNA levels were also reduced in Barrett's Esophagus (BE), a precancerous lesion of esophageal adenocarcinoma (EAC), and were reduced further in EAC (right panel from Oncomine)." (PMID 27081034, 2016).
colorectal adenocarcinoma (1 paper, 2016). The most common type of colorectal carcinoma. "For instance, PRSS8 protein level was highly expressed in well differentiated colorectal adenocarcinomas and was lower or absent in poorly differentiated colorectal adenocarcinomas (p<0.00001)." (PMID 27050145, 2016).
colorectal adenoma (1 paper, 2016). An adenoma that arises from the colon or rectum. "Since reduced expression of PRSS8 was seen in colorectal adenoma and adenocarcinoma, we then determined whether PRSS8 expression was linked to clinicopatholgical characteristics and outcomes." (PMID 27050145, 2016). "Herein we found that PRSS8 expression was significantly reduced in colorectal adenomas and adenocarcinomas." (PMID 27050145, 2016). "Notably, the expression of PRSS8 was reduced in colorectal adenoma, a pre-cancer lesion." (PMID 27050145, 2016).
COVID-19 (1 paper, 2024). A disease caused by infection with severe acute respiratory syndrome coronavirus 2. "With our own findings coinciding with the current literature, LGALS9, LAMP3, PRSS8 and AGRN prove to be potential biomarkers of health risk in COVID-19 patients, both individually and collectively." (PMID 39334929, 2024). "In conclusion, our study demonstrates that LGALS9, LAMP3, PRSS8 and AGRN are highly significant, differentially regulated plasma proteins found in hospitalised COVID-19 patients." (PMID 39334929, 2024). "Our results also coincide with these published findings and show that LGALS9, LAMP3 and PRSS8 are more expressed in hospitalised COVID-19 patients compared to non-hospitalised ones and demonstrated its utility as a predictive biomarker of health risk." (PMID 39334929, 2024). "FSTL3 has been implicated as a marker of COVID-19—CVD complications; however, no SNPs were found to be significantly correlated with hospitalisation for LGALS9, LAMP3, PRSS8 or AGRN." (PMID 39334929, 2024).
dementia (1 paper, 2025). Loss of intellectual abilities interfering with an individual's social and occupational functions. "Overall, 30 cSVD-associated proteins (61%) were associated at P < 0.05 and 18 at PFDR < 0.05 with stroke or dementia (both for PILRA and PRSS8)." (PMID 41266628, 2025).
emphysema (1 paper, 2016). "Consistently, supplemental analysis revealed that heterozygous deletion of CAP-1/prostasin/Prss8, one of the major CAPs that positively regulates ENaC, did not improve COPD/CF-like phenotypes such as emphysema and lung dysfunction." (PMID 27982104, 2016).
esophageal squamous cell carcinoma (1 paper, 2016). Esophageal squamous cell carcinoma (ESCC) is a type of esophageal carcinoma (EC) that can affect any part of the esophagus, but is usually located in the upper or middle third. "Herein we found that the expression of PRSS8, a serine protease prostasin, is significantly decreased in esophageal squamous cell carcinomas (ESCC) at mRNA and protein levels." (PMID 27081034, 2016). "Taken together, our findings have demonstrated that PRSS8 methylation and its stromal expression has important clinical significance in esophageal squamous cell carcinoma." (PMID 27081034, 2016).
esophageal tumors (1 paper, 2019). "In esophageal tumors, PRSS8 downregulation is related to DNA methylation." (PMID 31731486, 2019).
Glucose intolerance (1 paper, 2021). Glucose intolerance (GI) can be defined as dysglycemia that comprises both prediabetes and diabetes. "Aiming to explore the mechanism by which PRSS8 overexpression improves HFD-induced glucose intolerance and hepatic, we established cell lines using a doxycycline (Dox)-inducible gene expression system in HepG2 cells (Tet-on HepG2)." (PMID 34361079, 2021). "Altogether, our observations suggest that hepatic overexpression of PRSS8 protects mice from HFD-prompted glucose intolerance, in a manner independent of their BW." (PMID 34361079, 2021).
Hyperkalemia (1 paper, 2022). An abnormally increased potassium concentration in the blood. "In aldosterone-synthase knockout mice, diminished urinary K+ excretion, severe hyperkalemia, and food avoidance were observed, whereas our CAP1/Prss8 knockout mice showed normalized Na+ and K+ balance (data not shown) caused by low but still residual aldosterone concentration." (PMID 35743186, 2022).
Hyperkeratosis (1 paper, 2013). Hyperkeratosis is a histopathological term defining a thickened stratum corneum and may be present in many different skin conditions, with many possible overlaps. "Nevertheless, those pups were born with an hyperkeratosis as seen in newborns lacking CAP1/Prss8 expression in the epidermis, thus causing death shortly after birth." (PMID 23405214, 2013).
Hypertension (1 paper, 2023). The presence of chronic increased pressure in the systemic arterial system. "CAP1/Prss8 was linked to hypertension in rats when overexpressed, to a moderate increase of human blood pressure in a genetic variant of CAP1/Prss8, and proposed as a urinary candidate marker of ENaC activation in humans." (PMID 37830556, 2023).
melanoma (1 paper, 2004). A malignant, usually aggressive tumor composed of atypical, neoplastic melanocytes. "We identified a number of overexpressed genes previously associated with ovarian and other cancers including VEGF, osteopontin (OP), preferentially expressed antigen in melanoma (PRAME), TACSD2 (or GA733-1) and prostasin (PRSS8)." (PMID 14760385, 2004).
nephrotic syndrome (1 paper, 2022). A collection of symptoms that include severe edema, proteinuria, and hypoalbuminemia; it is indicative of renal dysfunction. "In this study, we used genetically modified knock-in mice with Prss8 mutations abolishing its proteolytic activity (Prss8-S238A) or prostasin activation (Prss8-R44Q) to investigate the development of sodium retention in doxorubicin-induced nephrotic syndrome." (PMID 35312839, 2022). "To study the in vivo relevance of prostasin’s role in ENaC-mediated sodium retention in nephrotic syndrome, we studied knock-in mice with enzymatically inactive (Prss8-S238A) or zymogen-locked prostasin (Prss8-R44Q)." (PMID 35312839, 2022). "After induction of nephrotic syndrome, the expression of full-length α-ENaC was increased in Prss8-wt mice, an effect not reaching significance in Prss8 mutant mice." (PMID 35312839, 2022).
ovarian tumors (1 paper, 2016). "In an analysis of nearly 500 ovarian tumors and normal ovarian tissues by In situ hybridization and Immunohistochemical staining in Tissue Array format, we found that the PRSS8 gene and PRSS8 protein (prostasin) were both significantly upregulated in the majority of ovarian tumors." (PMID 27036110, 2016).
pituitary tumor (1 paper, 2019). A benign or malignant neoplasm affecting the pituitary gland. "In addition, we looked at genes that were not previously investigated in pituitary tumors, FAM163A, HIF3A, and PRSS8, which were hypermethylated in NFPAs." (PMID 31731486, 2019).
primary aldosteronism (1 paper, 2022). An endocrine disorder characterized by excessive production of aldosterone by the adrenal glands. "The expression of urinary CAP1/Prss8 is enhanced in rats infused with aldosterone and in patients with primary aldosteronism, possibly leading to increased ENaC-mediated Na+ reabsorption in the distal nephron." (PMID 35743186, 2022).
Stroke (1 paper, 2025). Sudden impairment of blood flow to a part of the brain due to occlusion or rupture of an artery to the brain. "As reported by others, for six proteins we observed opposite directionality of associations for plasma versus CSF protein levels (APOE, EPO, PSMP, PRSS8 and TFPI with WMHs, IL-6 with HIP-PVS, and BT3A2 with stroke)." (PMID 41266628, 2025).
type 2 diabetes (1 paper, 2021). "On a distinct note, in humans, serum PRSS8 concentration was evidently inferior in patients with type 2 diabetes than that in healthy ones." (PMID 34361079, 2021).
cancer (21 papers, 2009 to 2025). A tumor composed of atypical neoplastic, often pleomorphic cells that invade other tissues. "In total, 10 proteins had an estimated AUC of at least 0.7 and were significantly associated with cancer status, including hK11, PRSS8, IL-6, MK, and CXCL13." (PMID 29051715, 2017). "The serine protease CAP1/Prss8 is crucial for skin barrier function, lung alveolar fluid clearance and has been unveiled as diagnostic marker for specific cancer types." (PMID 23405214, 2013). "Importantly, PRSS8 expressed in epithelia was greatly associated with cancer differentiation." (PMID 27081034, 2016). "Interestingly, the reduction of PRSS8 was positively associated with cancer differentiation." (PMID 27050145, 2016). "PRSS8 is a serine protease that plays a crucial role in maintaining skin integrity and facilitating the spread of cancer cells." (PMID 39765560, 2024). "Moving forward, we focused on HMOX1 and PRSS8, which have been shown previously to regulate cell survival in various cancer contexts." (PMID 36457077, 2022). "While PRSS8 has clearly been shown to promote apoptosis in multiple cancer contexts through regulation of several relevant proteins (PTEN, Bax, and MMP9), the role of HMOX1 in regulating apoptosis appears to vary across tissues." (PMID 36457077, 2022). "PRSS8 mRNA levels were reduced about 65% in adenocarcinoma tissues compared with non-cancer tissues (p<0.01)." (PMID 27050145, 2016). "PRSS8 expression was analyzed in cancer tissue and corresponding normal samples from 18 major human tumor types from 390 individuals (TissueScan from Origene, data not shown)." (PMID 27036110, 2016). "Overexpressing PRSS8 inhibited cancer cell proliferation, led to cell cycle arrest at G1/G2 phase, and retarded cancer cell growth in nude mice." (PMID 27050145, 2016). "Most importantly, ESCC stromal expression levels of PRSS8 was significantly correlated with stromal lymphocyte infiltration and cancer progression." (PMID 27081034, 2016). "MTT assay showed that increasing PRSS8 expression inhibited cancer cell proliferation at 24 and 48 hours in both SW480 and HCT116 cell lines (p<0.05), compared to the cells transfected with empty vector." (PMID 27050145, 2016). "For example, PRSS8 was overexpressed in cancer-in-situ, and in well- and moderate-differentiated ESCC tissues, but the expression was dramatically reduced in the poorly differentiated ESCC tissues, the difference was significant (p<0.001)." (PMID 27081034, 2016). "De-methylation agent decitabine was able to restore PRSS8 expression, leading to the inhibition of cancer cell proliferation, motility, migration and cell cycle arrest." (PMID 27081034, 2016). "In vivo studies have further demonstrated a tumor suppressing role of PRSS8, including inhibition of tumor growth in nude mice and cancer cell proliferation, and cell cycle arrest." (PMID 27050145, 2016). "Herein we found that PRSS8 was significantly reduced in ESCC cancer tissues and cancer cells at protein and mRNA levels, and the reduction of expression was associated with poor differentiation and shorter survival time and disease-free time." (PMID 27081034, 2016). "Equally associated with cancer, matriptase seems to act as a tumor suppressor gene in vitro, an effect proposed to be mediated through CAP1/Prss8." (PMID 23405214, 2013). "Increased expression of the N-terminally extended, likely mis-targeted proteoform, at the expense of the canonical one, could reduce the availability of PRSS8 in the seminal fluid and thereby contribute to cancer progression." (PMID 40276932, 2025). "PRSS8 is thought to play different roles in different cancers." (PMID 39527152, 2024). "In conclusion, we have identified that PRSS8 acts as a tumor suppressor gene in ESCC, the hypermethylation of the promoter region leads to repression of expression, and reduced expression is significantly associated with cancer differentiation and survival." (PMID 27081034, 2016).